SOX2 (SRY-box transcription factor 2)
Diseases named in the same sentence as SOX2 in open-access papers (continued):
Sharing a sentence is not in itself a finding about the gene and the disease.
medulloblastoma (continued). "In addition, Manoranjan proposed that the inhibition of self-renewal pathways such as Bmi1 and Sox2 could explain the improved outcome in WNT medulloblastoma." (PMID 34577571, 2021). "Therefore, through SOX2 induction, Shh drives medulloblastomas cellular growth and proliferation." (PMID 24550888, 2014). "Importantly, neurosphere studies conducted with freshly isolated CD133− DAOY cells, as well as putative tumor-initiating, CD133+ DAOY cells, support the conclusion that SOX2 levels must be carefully regulated in order to maintain the proliferation of DAOY medulloblastoma cells." (PMID 22937156, 2012). "By targeting SOX2, the tumourigenicity and EMT traits were decreased in oral CSCs, and growth of medulloblastoma was also inhibited." (PMID 35055392, 2022). "For these studies, SOX2-inducible medulloblastoma (i-SOX2-ONS76) and prostate tumor (i-SOX2-LNcaP) cells were used." (PMID 35454854, 2022). "This is true for cells that express low levels of SOX2, such as LNCaP prostate tumor cells, or higher levels of SOX2, such as ONS76 medulloblastoma cells." (PMID 35454854, 2022). "Rare quiescent sox2(+) cells, which are enriched following anti-mitotic treatment (temozolomide, TMZ), drive tumour regrowth in a similar mouse model of medulloblastoma." (PMID 34571996, 2021). "We verified that the stem culture condition increased the expression of well-established MBSC markers CD133, FUT4, SOX2, NESTIN in all cell lines compared to the expression in medulloblastoma cells cultured in the presence of serum." (PMID 32316671, 2020). "In SHH medulloblastoma (MB), quiescent SOX2+ cells could cause relapse where high frequency of SOX2+ cells revealed an increase in therapy-resistant MPCs (e.g. cytarabine or vismodegib), a predictive signature of poor outcome in patients with SHH-medulloblastoma." (PMID 30517668, 2020). "SOX2 expression also indicates a potential role in the aetiology of paediatric tumours, including DIPG and SHH-type medulloblastoma." (PMID 29759978, 2018). "To examine the impact of JQ1 in further detail we treated c-MYC translocated D283 medulloblastoma cells with JQ1 and performed immunofluorescence for SOX2." (PMID 24796395, 2014). "Inhibition of PLK1 impaired tumor sphere formation of medulloblastoma cells and decreased the expression of SRY (sex determining region Y)-box 2 (SOX2) mRNA in tumor spheres indicating a possible role in targeting tumor inititiating cells." (PMID 22390279, 2012). "In addition, SOX2 expression in the Visium data identified positive cell populations in both major genetic clones A and B in PDX as well as throughout the human medulloblastomas." (PMID 39609432, 2024). "To confirm the effects of NRP1 inhibition with MR438 on medulloblastoma stem cells, we evaluated the expression of stem cell markers (CD15, CD133 and Sox2) as well as the self-renewal ability of medulloblastoma cells to form medullospheres after tumor dissociation." (PMID 36457009, 2022). "Our previous work has shown that SOX2 elevation in five cell lines representing three tumor types (prostate, pancreatic, and medulloblastoma) does not significantly perturb the cell cycle distribution of engineered cells despite inhibiting growth." (PMID 35454854, 2022). "A lesser expression of both Bmi1 and Sox2 is observed in WNT medulloblastoma BTICs compared to non-WNT cells." (PMID 34577571, 2021). "SOX2 is also overexpressed or amplified in oligodendrogliomas and GBMs, and interestingly appears to be more highly expressed in the SHH-activated subgroup of medulloblastomas, perhaps suggesting a link between SHH and SOX2 signaling in a neoplastic context." (PMID 34012965, 2021). "Sox2+ cancer propagating cells (CPCs), capable of driving tumour initiation and exhibiting enhanced resistance to cytostatic therapy have been identified in SHH medulloblastoma mouse models." (PMID 31924815, 2020).
medulloblastoma (continued). "Notably, mithramycin downregulated SOX2 and ZEB1 in sarcoma cells, and effectively inhibited growth of a SOX2-positive cell population that propagates medulloblastoma." (PMID 31910904, 2020). "Excitingly JQ1 was effective in depleting SOX2 positive tumor cells in vivo and in decreasing SOX2 mRNA expression further confirming that BRD4 inhibition suppresses the tumor stem cell phenotype in medulloblastoma." (PMID 24796395, 2014). "Therefore, we predicted that OCT4 itself is capable of reprogramming the DAOY medulloblastoma cells via a network leading to the expression of OCT4, SOX2, and NANOG." (PMID 24202329, 2013). "In addition to i-SOX2-LNCaP and i-SOX2-ONS76, characterization of three additional engineered i-SOX2 tumor cell lines indicated that elevating SOX2 decreases MYC mRNA and protein in five tumor cell lines representing three human cancer types (prostate, medulloblastoma, and colorectal)." (PMID 35454854, 2022). "Mechanistically, SOX2 is necessary for maintaining GSC properties in GBM and medulloblastoma cells, but is not sufficient to support self-renewal properties again highlighting a role for TFs in tumor progression but not tumor initiation." (PMID 34012965, 2021).
brain tumors (54 papers, 2006 to 2025). "There is also an association between highly tumorigenic cell subsets in brain tumors and the expression of the markers nanog, nestin, Oct4, and Sox2." (PMID 37833934, 2023). "This is not only true in ESC, SOX2 has also been shown to associate with a diverse array of functionally distinct proteins in brain tumor cells." (PMID 28388544, 2017). "Not surprisingly, knockdown of the RNA binding protein Musashi 2 or the deubiquitinating enzyme USP9X, which have been shown to associate with SOX2 in multiple cell types, disrupts the self-renewal of ES cells and inhibits the growth of brain tumor cells." (PMID 27145457, 2016). "Levels of Sox2 upregulation appear to correlate with aggressive tumor behavior and knockdown of Sox2 in brain tumor stem cells results in a loss of self-renewal, invasion, and migration of these cells." (PMID 25713758, 2015). "Equally important, our data suggests that increases in the expression of SOX2 during brain tumor progression are likely to be linked closely with changes in other critical genes that work in concert with SOX2 to enhance the tumorigenicity of brain tumors." (PMID 22937156, 2012). "The coexpression of OCT4 and SOX2 in the context of in vivo GBM cells is also important to clarify the role of these genes in important biological processes associated with the development of these brain tumors." (PMID 35274101, 2022). "In addition, our study shows that SIX1 promotes stem-like or undifferentiated phenotypes in fibroblastic and brain tumor cells, linked to the regulation of the stemness factor Sox2." (PMID 30723235, 2019). "Given that SOX2 associates with a diverse array of essential proteins, it is likely that proteomic analysis of the SOX2-interactome in brain tumor cells could help identify additional proteins that influence the growth of these tumors." (PMID 23667531, 2013). "Therefore, we compared SOX2-interactomes identified in each of these cellular contexts, because proteins that associate with SOX2 in multiple cellular contexts are also likely to play essential roles in the behavior of brain tumor cells." (PMID 23667531, 2013). "Sox2 expression in brain tumor tissues is characteristic of both stem and differentiated cells; it is necessary to maintain a sufficient level of plasticity, allowing their transition between these states." (PMID 38672482, 2024). "Expression of the embryonic stem cell markers nanog, nestin, Oct4, and Sox2 is critical for the progression of various human malignancies, including brain tumors." (PMID 37833934, 2023). "Orthotopic implantation of BTIC-18 in mice led to a reliable formation of brain tumors that still expressed the proneural progenitor marker SOX-2 (sex determining region Y-box2) and the astrocytic marker GFAP." (PMID 36834608, 2023). "Brain tumors derived from either SOX2-depleted or control cells showed similar Ki67, TUNEL and CD34 staining." (PMID 35737114, 2022). "We observed that about half of qProm1 cells express also SOX2, suggesting the possible co-existence of two different quiescent populations, Prom1+/SOX2+ and Prom1+/SOX2-, as also observed in human brain tumor samples." (PMID 35970913, 2022). "Collectively, SES produces a significant silencing of a large fraction of the SOX2 transcriptional network, achieving high levels of efficacy in repressing aggressive brain tumors." (PMID 35921410, 2022). "It was further supported by using lipopolymeric nanoparticle-containing combo siRNA (OLIG2, POU3F2, SALL2, and SOX2) targeting brain tumor-initiating cells (BTICs) in a mouse brain tumor model." (PMID 34944911, 2021). "This has been shown for SOX2+ cells in normal tissue as well as for the SOX2+ subpopulation found within brain tumor." (PMID 34947991, 2021). "With respect to survival, SOX2 expression is positively correlated with brain tumor malignancy grade and confers poor clinical outcomes." (PMID 34012965, 2021).
brain tumors (continued). "Neuronal SOX2 peaks, in contrast, showed an enrichment for the homeodomain HOX motif, found in developmental TFs, and ARID3B motif, an AT-rich interaction domain factor overexpressed in neuroblastomas and interacting with SOX2 in brain tumors." (PMID 32553182, 2020). "Of the three longevity-related factors, SOX2 seems to be the playmaker in the development of brain tumors." (PMID 29849920, 2018). "A mouse model revealed that SOX2 is required for the maintenance of CSCs in high grade oligodendroglioma, thus, affirming the potential importance for SOX2 in brain neoplasm tumorigenicity." (PMID 29642503, 2018). "T3M4 cells were engineered for inducible overexpression with the aid of two lentiviral vectors, which are similar to those used previously to engineer brain tumor cells for inducible expression of exogenous SOX2." (PMID 27145457, 2016). "Knockdown of SOX2 impaired growth and tumorigenicity in brain tumor cells, but surprisingly, a 3-fold elevation above endogenous levels impaired proliferation." (PMID 25340937, 2014). "Relevant to the work described in this study, elevated levels of the transcription factor SOX2, which plays critical roles in the development of the nervous system, have been shown to correlate with poor clinical outcome for brain tumor patients." (PMID 23667531, 2013). "Even within different types of brain tumor cells, the SOX2-interactome appears to be context dependent." (PMID 23667531, 2013). "The critical role of SOX2 in brain tumors is supported by the finding that knockdown of SOX2 by RNA interference reduces the in vitro and in vivo growth of GB cells." (PMID 23667531, 2013). "The differences observed in the sensitivity of these brain tumor cell lines to exogenous SOX2 (introduced by lentiviral transduction) is likely to be due, at least in part, to differences in the transduction efficiencies of the various cell lines." (PMID 22937156, 2012). "Brain tumor cells expressing SOX2 also have regulatory mechanisms in place to restrain its aberrant expression." (PMID 22937156, 2012). "Although knockdown of SOX2 impairs the growth and tumorigenicity of brain tumor cells, it was unclear how elevating SOX2 levels would affect their fate." (PMID 22937156, 2012). "The increase in SOX2 levels induced in MCF7 and MDA-231 cells (∼2- to 3-fold) were similar to the levels of SOX2 in MCF7 cells engineered to stably overexpress SOX2, as well as the level of SOX2 induction observed in our brain tumor studies presented above." (PMID 22937156, 2012). "Our findings with brain tumor cells raised an important question: do brain tumor cells respond differently to increases in SOX2 than other types of tumors?" (PMID 22937156, 2012). "In conclusion, the findings described in this study underscore the importance of carefully regulating the expression and function of the essential transcription factor SOX2 in brain tumor cells." (PMID 22937156, 2012). "A recent study revealed robust SOX2 expression in brain tumors of glial lineages expressing the astrocytic marker protein glial fibrillary acidic protein (GFAP)." (PMID 22070920, 2011). "In addition to these factors, SOX2 is also a crucial component of the transcriptional circuitry in some kinds of brain tumor such as DMG, AT/RT, and SHH-MB, and maintains neural stemness and developmental potency in tumor cells." (PMID 40599851, 2025). "In our opinion, the identified negative association between Cd44 and Sox2 will require further investigation because it indirectly indicates the presence of several types of cells with stem characteristics in brain tumors." (PMID 38672482, 2024). "Transcriptomic analyses showed that OCT4A, NANOG, and SOX2 were overexpressed in brain tumors." (PMID 35565225, 2022). "Sox2 and its family members activate signaling pathway molecules and pluripotent transcription factors that directly or indirectly influence neuron protection as well as control its expression to treat brain tumors in humans and mice." (PMID 34150525, 2021).
brain tumors (continued). "Among these, we have shown that genes related to pluripotency, such as Sox2, Nanog, and Oct4, were indeed regulated by Elk-1, and in the context of brain tumors, we further showed that Elk-1 overexpression in CD133+ BTIC population results in the upregulation of these genes." (PMID 33672811, 2021). "Both cell types produced brain tumors that contained Sox2+ cells, indicative of tumor stem cells." (PMID 26659251, 2016). "Of these three TFs, SOX2 appears to be a key player in both the normal brain and brain tumours." (PMID 26580604, 2015). "In view of the potent ability of SOX2 to dramatically alter the fate of NSC shortly following its elevation, we hypothesized that brain tumor cells must also tightly control the levels of SOX2 in order to support their growth." (PMID 22937156, 2012). "Moreover, our studies suggest that overexpression of SOX2 imparts a significant stress upon brain tumor cells." (PMID 22937156, 2012). "Previous reports provide insight into regulatory mechanisms that may be essential for the careful regulation of SOX2 in brain tumors." (PMID 22937156, 2012). "Thus, it is likely that regulatory mechanisms, which suppress the aberrant expression of SOX2 in other neural tissues, must be modified to support the long-term expression of SOX2 in brain tumor cells." (PMID 22937156, 2012). "When performing IHC staining of mouse brain tumors, an almost complete overlap between SOX2 and miR-21 expression could be seen." (PMID 22931209, 2012). "In addition to the ZIKV receptors, we further characterized all cell lines for the expression of embryonic stem cell markers Nanog, Nestin, Oct4, and Sox2, as these are critical receptors for the progression of various human malignancies, including brain tumors." (PMID 38398205, 2024). "Our data, showing that Sox2+ cells in the DG were significantly decreased during acute colitis and unchanged during the chronic phase, ruled out the possibility that gut inflammation might promote brain tumor development, at least in our experimental setting." (PMID 36232813, 2022). "Therefore, SOX2 silencing might be a novel therapeutic approach to combat cancer and particularly brain tumors." (PMID 27822457, 2016). "Further IHC staining of tumor for HGA markers including GFAP, Sox2, nestin, and Ki-67 confirmed the HGA status of the brain tumors." (PMID 35814428, 2022). "We performed flow cytometric characterization of CD133, Sox2, and CD15, three markers that have reproducibly been shown to mark TICs in a number of pediatric and adult brain tumors." (PMID 27894339, 2016). "While it is theoretically possible that the neural stem cell marker Sox2 could be expressed in two separate cell populations (neural progenitor cells and reactive astrocytes) which share the same anatomic location with respect to brain neoplasms, it seems unlikely." (PMID 25713758, 2015). "Our data suggest that miR-21 regulates SOX2 and is important in maintaining PDGF-driven brain tumors that constitute the large proneural subgroup of human malignant glioma." (PMID 22931209, 2012). "Together, our findings with SOX2 and those observed at low oxygen levels raise the possibility that CD133 plays an important role in the stress response of brain tumor cells in particular, and in cellular physiology in general." (PMID 22937156, 2012). "We then evaluated the expression of SOX2 and FOSL2 in different subtypes of lung and brain tumors." (PMID 36932385, 2023). "In our own lung metastatic brain tumor sample set, SOX2 was not among genes focally amplified according to GISTIC analysis, but tumors with SLITRK3 amplification displayed SOX2 copy number gains (data available at GSE157515)." (PMID 35006496, 2021). "More recently, a Zika OV was shown to specifically target GBM stem cells (GSCs) rather than neural precursor cells, through a SOX2-Integrin αvβ5 Axis, suggesting a potentially superior anti-tumoral activity for brain tumor therapy." (PMID 33154756, 2020).
brain tumors (continued). "However, it is noteworthy that the CSC in both, adult, and the pediatric brain tumors, retain the functionality of pluripotency-biomarkers such as NANOG, SOX2, and OCT4." (PMID 33137926, 2020). "Furthermore, miR-21 and SOX2 showed up-regulation and overlapping expression pattern in RCAS/tv-a generated mouse brain tumor specimens." (PMID 22931209, 2012). "On serial sections from one individual mouse brain we could see that SOX2 was also co-expressed with OLIG2, which is a surrogate marker for brain tumor cells." (PMID 22931209, 2012). "Other brain tumors, such as medulloblastomas and pineoblastomas, displayed markers of neuronal differentiation and lacked SOX2 expression." (PMID 22070920, 2011). "Thus, the impairment of tumor cell growth following elevation of SOX2 is not unique to brain tumor cells." (PMID 22937156, 2012). "This does not diminish the importance of SOX2 expression in prostate, breast or brain tumor cells." (PMID 22937156, 2012). "SOX2 could not be detected in cortex areas, which were not affected by tumour cell invasion, or in cortex tissue obtained from four control cases without brain tumours or other pathological findings in the brain." (PMID 17375044, 2007). "Importantly, overexpression of SOX2 in brain tumor cells and PDAC cells from an inducible promoter does not reduce expression of the endogenous SOX2, which suggests that the negative feedback loop is not active in at least some tumor cells." (PMID 28388544, 2017).